PIN1 (peptidylprolyl cis/trans isomerase, NIMA-interacting 1)
Diseases named in the same sentence as PIN1 in open-access papers (continued):
Sharing a sentence is not in itself a finding about the gene and the disease.
tumor (163 papers, 2008 to 2026). "Co-culture experiments directly linked tumor cell Pin1 to CAF function: Pin1-knockdown tumor cells reduced FAP expression, and CAFs activated by these cells showed impaired ability to suppress IFN-γ+ CD8+ T cells in PBMC co-cultures." (PMID 41246306, 2025). "PIN1 is recognized as a master regulator of malignant processes and is closely associated with tumor cell metabolic reprogramming, proliferation, migration, drug resistance, stem cell-like characteristics, and TME regulation." (PMID 41246306, 2025). "Pin1 is a pivotal player in interactions with a diverse array of phosphorylated proteins closely linked to critical processes such as carcinogenesis and tumor suppression." (PMID 38318109, 2024). "PIN1 KO dramatically reduced cell viability in long-term clonogenic assays in both RB-proficient and RB-deficient BC cell lines, indicating PIN1 KO induced RB-independent effects on tumor cells growth." (PMID 38622115, 2024). "Abnormal regulation of Pin1 exerts a profound effect on cell fate, and is therefore associated with the development of various diseases, tumorigenesis, and tumor development." (PMID 35461311, 2022). "Prolyl isomerase 1 (PIN1) is overexpressed in a variety of tumors, and is closely associated with the malignant potential of tumor cells, such as transformation, proliferation, invasion and metastasis." (PMID 35983979, 2022). "PIN1 regulates protein function via conformational changes of target protein and is associated with the oncogenic pathway activation by controlling tumor suppressors and oncogenes." (PMID 32258027, 2020). "By contrast, DAPK1, a known tumor suppressor, associates with and phosphorylates Pin1 on Ser71, which suppresses Pin1 nuclear localization and sustains cell cycle by activating cyclin D1 promoter in cells." (PMID 32296699, 2020). "According to published results, PIN1 was shown to boost dozens of oncogenes or factors that promote proliferation, while inactivating several tumor suppressors, but which are the deranged underlying cellular processes is still incompletely understood." (PMID 30873382, 2019). "Pin1 overexpression also causes centrosome amplification, chromosome instability and tumor development in vitro and in vivo." (PMID 31015482, 2019). "Higher PIN1 expression is significantly associated with larger tumor size, increased intrahepatic metastasis and portal vein invasion." (PMID 32010690, 2019). "The phosphorylation on Ser71 by DAPK1 (Death-associated protein kinase 1), a known tumor suppressor, inhibited Pin1 catalytic activity during the cell cycle progression." (PMID 30096758, 2018). "Collectively, these results not only demonstrate that Pin1 down-regulation is a key event underlying the anti-tumor effects of sorafenib, but also uncover that Pin1 inhibitors offer a novel approach to enhance the therapeutic efficacy of sorafenib against HCC." (PMID 28404959, 2017). "In this study, constitutive PIN1 overexpression was found in EBV-associated NPC tumor cells, but PIN1 protein was scarcely detected in EBV-negative nasopharyngeal epithelial cells." (PMID 27258148, 2016). "Mounting evidence indicates that Pin1 plays a critical role in tumor-associated angiogenesis." (PMID 33807199, 2021). "Consequently, PIN1 over-expression has been linked to dysregulated cell proliferation, malignant transformation and tumor development." (PMID 32010690, 2019). "Similarly, high PIN1 expression is associated with tumor progression in colorectal and nasopharyngeal cancer." (PMID 30314361, 2018). "Notably, our data not only extend the role of Pin1 in regulating several members of Notch receptor family but underline the cell- (or tumor-) dependent context of Pin1 mechanistic activity." (PMID 26876201, 2016).
tumor (continued). "In addition, paclitaxel treatment induced caspase-3 cleavage that was strongly increased by Pin1 silencing, indicating that reduced levels of Pin1 synergize with paclitaxel in inducing apoptosis and hence causing maximal tumor shrinkage." (PMID 24357640, 2014). "The Pin1-regulated alteration in protein interactions and stability have been shown to be associated with cell transformation and progression of certain types of human tumours (e.g., prostate, colon, lung, ovary and breast cancers, and lymphoma)." (PMID 21219594, 2011). "However, the ability to induce degradation of pro-oncogenic proteins such as c-Myc and cyclin-E suggests that, depending on the combination of genetic and epigenetic alterations underlying the pathology, Pin1 may cooperate with tumor suppression as well." (PMID 28426725, 2017). "PIN1 is overexpressed in HCC, particularly in HBV-related HCC, and is associated with adverse features such as increased tumor sizes, intrahepatic metastasis, and poor prognoses." (PMID 41438340, 2026). "•SENP1 regulates CSC-associated properties in HCC, including OCT4, CD133, PIN1, the EMT, and tumor metastasis." (PMID 41438340, 2026). "Co-expression of Pin1 and HBx leads to increased cell proliferation and tumor growth, whereas knockdown of Pin1 impairs HBx-induced tumor formation." (PMID 40332052, 2025). "We subcutaneously inoculated CT26 cells into mice and injected Pin1 inhibitor or αPD1/Pin1 inhibitor combination therapy into tumor-bearing mice." (PMID 41246306, 2025). "To further verify that the observed activity was due to direct inhibition of Pin1 in vivo, we analyzed tumor tissues to measure 164B8 levels and Pin1 degradation in both tumor and normal tissues." (PMID 41322199, 2025). "Based on these premises, potential therapeutic targeting for PDAC includes inhibition of Pin1 in tumor cells and in CAFs." (PMID 41322199, 2025). "Pin1 is a cell cycle enzyme, which is overexpressed in a variety of tumor cells, but a reduction in soluble Pin1 in AD hippocampal brain tissue has been found." (PMID 40149482, 2025). "Collectively, these results suggest Pin1 inhibition reduces MSS CRC tumor growth through enhanced CD4+/CD8+ T cell accumulation and reduced Treg recruitment." (PMID 41246306, 2025). "Our findings indicate that Pin1 inhibitor monotherapy significantly reduced tumor volume and weight, while combination therapy produced stronger inhibition." (PMID 41246306, 2025). "Flow cytometry analysis of tumor-infiltrating immune cells showed that Pin1 inhibitor monotherapy increased infiltration of CD3+ lymphocytes, CD8+ T cells, and CD4+ T cells." (PMID 41246306, 2025). "The results demonstrated that the combined therapy of Pin1 inhibitor and anti-PD-1 antibody significantly suppressed tumor progression." (PMID 41246306, 2025). "In numerous tumor types, Pin1 accelerates tumor development and correlates with unfavorable patient prognosis." (PMID 41246306, 2025). "It has been reported that targeting Pin1 on CAFs can reduce collagen deposition, tumor growth, and CAF activation and proliferation by inhibiting lysosomal degradation of PD-L1 and ENT1 in tumor cells and activating other cancer-associated pathways." (PMID 40521175, 2025). "This demonstrates that the expression of Pin1 in tumor cells reprograms CAFs to foster an immunosuppressive TME." (PMID 41246306, 2025).
tumor (continued). "Pin1 is thought to potentially regulate protein function and impact cell cycle regulation and tumor formation." (PMID 41246306, 2025). "Starting from day 7 post tumor inoculation, the mice received daily injections of the Pin1 inhibitor and injections of the anti-PD-1 antibody every 3 days." (PMID 41246306, 2025). "Astonishingly, the combination of Pin1 inhibitors and immunochemotherapy achieved over 85% tumor eradication after 1 year even with only 4 months of the treatment, compared with 0% in the immunochemotherapy group alone." (PMID 38745861, 2024). "The overexpression of Pin1 in tumor cells was positively correlated with tumor stem cells progression." (PMID 38285118, 2024). "Peptidyl-prolyl cis-trans isomerase NIMA-interacting 1 (PIN1)-catalyzed phosphorylation-dependent cis-trans prolyl isomerization drives tumor malignancy." (PMID 38622115, 2024). "Through stabilizing or destabilizing its target, Pin1 can increase the activation of over 70 oncogenes as well as inactivate over 30 tumor suppressors." (PMID 38745861, 2024). "By upregulating the levels of hypoxia inducible factor (HIF), Pin1 participates in potentiating tumor hypoxia responses." (PMID 38167292, 2024). "Pin1 plays essential roles in regulating Pro-directed phosphorylation and controlling tumor inhibitors." (PMID 39624096, 2024). "In this section, we will explore recent discoveries in the Pin1 enhancement of oncogene stability and tumor suppressor degradation." (PMID 38727267, 2024). "In contrast to its multifaceted roles as a tumor-promoting enzyme, Pin1 has also been described as a “conditional” tumor suppressor." (PMID 38745861, 2024). "In clinical settings, METTL3 expression is significantly increased with tumor progression and is positively correlated with PIN1 expression in BC tissues." (PMID 38961497, 2024). "Pin1 often regulate the protein stability or change the subcellular localizations of substrate proteins, mostly powerful oncogenes, to promote tumor growth." (PMID 38167292, 2024). "Abnormal Pin1 activation disturbs the equilibrium between oncogenic and tumor-suppressing molecules, favoring oncogenesis." (PMID 38534454, 2024). "Pin1 is highly expressed in tumor cells, and the expression level in BCSCs is 30 times higher than in common tumor cells." (PMID 38285118, 2024). "Collectively, our data demonstrate that PIN1 plays an important role as a tumor suppressor in response to oncogenic ER:RasG12V activation." (PMID 38216124, 2024). "Significantly, by combining Pin1 and CDK4 inhibitors to prevent APC/CCDH1 inactivation, the APC/CCDH1 induces the degradation of Pin1 and other mitotic proteins, forcing the cells into cell cycle arrest and triggering increased anti-tumor immune activity." (PMID 38727267, 2024). "Together, these results shed light on a potential mechanism by which PIN1 depletion leads to cellular proliferation, senescence bypass, and potential tumor initiation." (PMID 38216124, 2024). "Our data show that combined inhibition of CDK4 and PIN1 permits deeper and longer-lasting remissions, even resulting in complete remission in some tumor-bearing mice." (PMID 38622115, 2024). "As2O3 treatment substantially repressed tumor growth after treatment initiation, finaltumor weight at necropsy, and Pin1 expression (82.2–96.2% PBS control)." (PMID 39051165, 2024).
tumor (continued). "A DNA-barcoded micellular system (DMS) functionalized with CAFs-targeting anti-FAP antibodies (antiCAFs-DMS) can selectively inhibit PIN1 in CAFs, leading to efficacious but transient tumor growth inhibition." (PMID 38892190, 2024). "PDAC was shown to be eradicable for the first time by targeting Pin1, which renders the immune “cold” tumor environment “hot” and sensitizes PDAC to immunochemotherapy." (PMID 38745861, 2024). "The second, PIN1, is a member of the parvulin family that modulates a large subset of key oncogenes and tumor suppressors by catalyzing the cis/trans isomerization of specific pSer/Thr-Pro motifs." (PMID 38627659, 2024). "In mouse embryonic stem cells (ESCs), Pin1 inhibition reduced tumor size by decreasing the self-renewal and teratoma-forming potential of ESCs in immunodeficient hosts." (PMID 38745861, 2024). "Recently, Pin1 was found to promote tumor cell survival by stabilizing nuclear factor erythroid 2–related factor 2 (Nrf2)." (PMID 38727267, 2024). "Depletion of Pin1 activity in human tumor cells and deletion of ESS1 in S. cerevisiae result in mitotic arrest." (PMID 37050909, 2023). "The tumoricidal effects of small-molecule Pin1 inhibitors suggest Pin1 plays a pivotal role in tumor development." (PMID 38020885, 2023). "PIN1 has been reported to regulate tumorigenesis and tumor progression by stabilizing several oncogenic proteins such as p65 and β-catenin." (PMID 36813923, 2023). "We decided to investigate the role of the peptidylprolyl isomerase Pin1, since we previously reported that Pin1 enhanced the oncogenic activity and tumor progression of PCNSL." (PMID 38089883, 2023). "Taken together, these results suggest that PIN1 promotes tumor progression of TNBC both in vitro and in vivo at least in part through affecting the stability of pVHL." (PMID 36813923, 2023). "The relationships between TPL2 and Pin1 expression with patient age, Ki67 positive index, histological grading, tumor size, lymph node metastasis, TNM stage, and positive ER/PR expression were analyzed in 80 IDC cases." (PMID 37833434, 2023). "We thus cannot rule out the possibility that additional mechanism is engaged in targeting PIN1 regulated tumor progression and metastasis." (PMID 36813923, 2023). "Similar results were obtained in experiments using NCCIT cells, suggesting that KPT6566 reduces the Pin1 level in a tumor cell type- and context-dependent manner." (PMID 38020885, 2023). "Overactivation of PIN1 disrupts the balance between oncogenic and tumor-suppressing proteins, shifting it toward oncogenesis." (PMID 37370134, 2023). "Our recent work demonstrated that small-molecule Pin1 inhibitors have antitumorigenic activity against colorectal cancer stem cells or tumor-initiating cells." (PMID 38020885, 2023). "Pin1 is a crucial enzyme for carcinogenesis because it suppresses tumour suppressors and activates oncogenes." (PMID 37372454, 2023). "Here, we show that PIN1 expression is positively correlated with tumor stiffness and the stromal proportion in PDAC." (PMID 36834887, 2023). "Pin1 also plays a crucial role in tumorigenesis mediated by CD44+CD133+ tumor-initiating Caco-2 cells." (PMID 35433695, 2022). "Pin1 activates many oncoproteins, simultaneously inactivates many tumor suppressors and downregulates global microRNA." (PMID 36619302, 2022). "We show that Pin1 plays a central role in promoting the tumorigenic potential of CD44+CD133+ tumor-initiating Caco-2 cells." (PMID 35433695, 2022). "DMS functionalized with CAF-targeting anti-FAP-α antibodies (antiCAFs-DMS) can selectively inhibit Pin1 in CAFs, leading to efficacious but transient tumor growth inhibition." (PMID 35879297, 2022). "In particular, targeting tumor-initiating cells using chemical Pin1 inhibitors provides a new option for management of CRC tumor-initiating cells." (PMID 35433695, 2022). "So, ATO absorption through AQP9 controls the capability to provoke Pin1 degradation and block tumor proliferation." (PMID 36077720, 2022).
tumor (continued). "Compared with the Ctrl or Ctrl+Sh-NC group, tumor tissues derived from the HG or HG + Sh-NC group exhibited increased positivity for Pin1, BRD4, NAP1L1, PCNA, and MMP9, and reduced positivity for P21." (PMID 35461311, 2022). "With regard to the underlying mechanism, it was reported that PIN1 is located in the nucleus and interacts with the glycolytic enzyme PGK1 to regulate tumor metabolism." (PMID 35983979, 2022). "Due to the critical roles of Pin1 in tumor initiation and progression, small molecules for inhibiting Pin1 have continuously been screened or developed." (PMID 35879297, 2022). "Pin1 enhances the stability of β-catenin and activates Wnt/β-catenin signaling to regulate tumor metabolic reprogramming." (PMID 33807199, 2021). "Although Pin1 inhibitors have shown tumor suppressive effects in cell lines, animal models, and even clinical trials, some inhibitors reveal a Pin1-independent mechanism and the side effects have yet to be clarified." (PMID 33537091, 2021). "PIN1-mediated isomerization alters the structure and activity of these proteins, regulating functions in cell metabolism, cell mobility, tumor development, oxidative stress and inflammation." (PMID 33407078, 2021). "There is evidence that EGCG is capable of binding to both functional domains of PIN1, WW and PPIase, leading to the suppression of tumour-promoting activity of PIN135." (PMID 33907248, 2021). "Taken together, these conformational modifications, which are induced by tumor-promoting signals or tumor-suppressive signals, regulate Pin1 functions to control diverse biological processes." (PMID 33807199, 2021). "Conversely, DAPK1, a tumor suppressor, phosphorylates Pin1 at Ser7, which leads to inhibition of catalytic activity and blockage of nuclear localization." (PMID 33807199, 2021). "Transforming growth factor (TGF)-β plays a critical role in tumor metastasis and Pin1 has been found to upregulate TGF-β by stabilizing its mRNA." (PMID 33807199, 2021). "Western blot analyses of tumor lysates confirmed the on-target activity of ATRA with decreased levels of Pin1 and its target cyclin D1." (PMID 33753863, 2021). "Expression of Pin1 in tumor cell lines cultured in vitro has also been found to be significantly higher than that in normal cell lines." (PMID 33537091, 2021). "Meanwhile, FKBP51, FKBP52, and PIN1 can play an important role in onocogenesis and tumor resistance to therapeutics." (PMID 32268506, 2020). "Consistently, tumor growth has been abrogated in a nude mouse xenograft model treated with Pin1 inhibitor and/or COT kinase inhibitor." (PMID 32195254, 2020). "For example, Pin1 has numerous protein substrates; possibly, interdomain flexibility helps Pin1 adapt to the conformational diversity presented by its varied substrates, which include both tumor suppressors and oncogenes." (PMID 32963105, 2020). "By regulating the activation of NF-κB, Pin1 promotes tumor progression and inflammatory cytokine production." (PMID 32266261, 2020). "In this review, we make a case that this anti-apoptotic role of cis-ATR supports oncogenesis, while Pin1 that drives the formation of trans-ATR suppresses tumor growth." (PMID 32426354, 2020). "Pin1 is a peptidyl‐prolyl cis/trans isomerase that functions in the oncogenic processes of various tumour cells." (PMID 32347623, 2020). "In this oncogenic context, the HDAC6 and Pin1 expression is regarded to involve in tumor progression and poor prognosis." (PMID 33162791, 2020).